IL6 (interleukin 6)
Diseases named in the same sentence as IL6 in open-access papers (continued):
Sharing a sentence is not in itself a finding about the gene and the disease.
Insulin resistance (continued). "For example, IL-6 promotes hepatic CRP production and vascular cell adhesion molecule (VCAM) expression; TNF-α contributes to endothelial dysfunction and insulin resistance; and IL-8 facilitates leukocyte recruitment to sites of injury." (PMID 40806281, 2025). "Resistin influences the synthesis of critical pro-inflammatory cytokines, including TNFα, IL6, and IL12, by activating NF-κB pathways in macrophages, leading to significant disruptions in peripheral insulin signaling and the development of insulin resistance." (PMID 40699839, 2025). "Visceral obesity and insulin resistance contribute to a pro-inflammatory state in which hypertrophied adipocytes and infiltrating immune cells secrete cytokines such as TNF-α, IL-6, and MCP-1." (PMID 40710574, 2025). "Despite these promising insights, the specific role and clinical relevance of IL-6 within the context of PCOS remain insufficiently understood, particularly regarding comparative analyses of IL-6 levels in patients with differing insulin resistance statuses." (PMID 40226143, 2025). "Typically, men possess a higher proportion of visceral fat and secrete more pro-inflammatory factors such as IL-6 and TNF-α, which promote insulin resistance and atherosclerosis." (PMID 40395813, 2025). "In particular, cytokines such as IL-6, IL-1β, TNF-α, and CRP contribute to the development of insulin resistance." (PMID 40283443, 2025). "VAT is metabolically active and contributes to systemic inflammation and insulin resistance by secreting increased amounts of pro-inflammatory adipokines, including tumor necrosis factor alpha (TNF-α) and interleukin-6 (IL-6)." (PMID 40013194, 2025). "Neuroinflammation is triggered through the release of some cytokines like interleukin 6 (IL-6) and tumour necrosis factor-alpha (TNF-alpha), which are products of inflammation and a key feature of insulin resistance, and they lead to cognitive impairment." (PMID 41280310, 2025). "Pro-inflammatory cytokines (e.g., IL-6, TNF-α) derived from adipose tissue not only exacerbate insulin resistance but also foster a tumor-promoting milieu in the endometrium, creating a biological continuum linking these conditions." (PMID 40718420, 2025). "Insulin resistance often triggers a state of low-grade chronic inflammation, activating immune cells and releasing pro-inflammatory cytokines like CRP, IL-6, and TNF-α." (PMID 40002771, 2025). "Chronic periodontitis-mediated insulin resistance and worsening of glycemic control are due to systemic inflammation and the release of pro-inflammatory cytokines such as TNF-α and IL-6 and other mediators by impairing insulin signaling pathways." (PMID 40136728, 2025). "IL-6 and TNF-α are known to influence lipid metabolism and GLUT4 expression, contributing to the development of insulin resistance." (PMID 40142333, 2025). "This inflammatory state, characterized by elevated levels of cytokines such as interleukin-6 (IL-6) and tumor necrosis factor-α (TNF-α), which in turn exacerbate oxidative stress and insulin resistance, thereby promoting tumorigenesis." (PMID 41567806, 2025). "Among the interesting cytokines and chemokines that decreased substantially, we found the well-known and highly pro-inflammatory cytokines IL-6, TNF, and IL-18 whose roles in adipose tissue-driven inflammation and insulin resistance are well-established." (PMID 40423925, 2025). "This proinflammatory cascade, driven by cytokines such as IL-6, TNF-α, and MCP-1, promotes macrophage infiltration and activates the NF-κB/JNK pathway, ultimately contributing to systemic insulin resistance." (PMID 41471698, 2025). "While IL-6 and TNF-α contribute directly to insulin resistance and inflammation, leptin plays an additional role in reproductive dysfunction by influencing ovarian steroidogenesis and follicular maturation." (PMID 40385768, 2025).
Insulin resistance (continued). "Simultaneously, the pro-inflammatory milieu of MASLD, characterized by elevated cytokines like IL-6 and TNF-α, further aggravates peripheral insulin resistance and pancreatic beta-cell dysfunction, directly fueling the progression of T2DM." (PMID 41441018, 2025). "While IL-6 and TNF-α promote insulin resistance and chronic inflammation, VEGF plays a dual role by contributing to both inflammation and pathological ovarian angiogenesis." (PMID 40385768, 2025). "Periodontitis has been shown to induce systemic inflammation via the release of inflammatory mediators, such as interleukin-6 (IL-6) and tumor necrosis factor-alpha (TNF-α), which exacerbate insulin resistance and glycemic dysregulation." (PMID 40458179, 2025). "In the case of insulin resistance, lipolysis occurs with the release of fatty acids that activate NFκB; therefore, TNF‐α and IL‐6 are expressed." (PMID 41387361, 2025). "This transition results in increased secretion of cytokines such as TNF-α, IL-6, and monocyte chemoattractant protein-1 (MCP-1), which collectively drive systemic meta-inflammation and can contribute to the development of insulin resistance." (PMID 41301434, 2025). "Systemic inflammation in COPD contributes to insulin resistance by increasing pro-inflammatory cytokines (TNF-α, IL-6, and CRP), which impair glucose metabolism and beta-cell function." (PMID 40142617, 2025). "Regarding insulin resistance, activation of PPARD has been reported to improve high-fat diet-induced insulin resistance via the IL-6/signal transducer and activator of transcription 3 pathway by increasing AMP-activated protein kinase activity in mice." (PMID 39899669, 2025). "VAT expansion increases proinflammatory cytokines (e.g., interleukin-6 [IL-6], tumor necrosis factor-alpha [TNF-α]), driving insulin resistance, and reduces adiponectin, exacerbating metabolic dysregulation." (PMID 41163040, 2025). "A broader evaluation of metabolic outcomes including insulin resistance, adipokines, and inflammatory markers such as C‐reactive protein (CRP) and interleukin‐6 (IL‐6) would provide a more comprehensive understanding of its systemic effects." (PMID 40887215, 2025). "Cachectic COPD phenotypes are marked by systemic inflammation (elevated IL-6 and TNF-α) and progressive muscle wasting, closely correlating with metabolic dysfunction and insulin resistance." (PMID 40283443, 2025). "The imbalance in immune cells contributes to the persistent secretion of pro‐inflammatory cytokines, such as MCP‐1, IL‐6, and TNF‐α, which induces insulin resistance and dyslipidemia." (PMID 41479855, 2025). "Furthermore, elevated TyG levels are frequently linked to chronic inflammatory responses, characterized by increased concentrations of proinflammatory cytokines such as TNF-α and IL-6, which may further impede insulin receptor signaling and exacerbate insulin resistance." (PMID 40626240, 2025). "NFκB activation further induces the release of pro-inflammatory cytokines such as IL-6, TNFα, ICAM-1, and VCAM-1, which ultimately exacerbates insulin resistance in diabetic patients." (PMID 40369521, 2025). "In adipocytes, insulin resistance and inflammation lead to synthesis and release of NEFA and pro-inflammatory cytokines, such as interleukin-6 (IL-6) or tumor necrosis factor (TNF)." (PMID 41012462, 2025). "Subsequently, inflammatory cytokines like tumor necrosis factor alpha (TNFα), interleukin 6 (IL6), and interleukin 1 beta (IL1β) exacerbate insulin resistance and metabolic dysfunction." (PMID 40687133, 2025). "Analysis biochemical indicators revealed significant post-treatment differences in LDL-C, TC, Hcy, IL-6, TNF-α, 25(OH)D, and insulin resistance (IR) (P < 0.05)." (PMID 40963681, 2025). "Among various inflammatory mediators, interleukin-6 (IL-6) and tumor necrosis factor-alpha (TNF-α) have been extensively studied for their contributions to both systemic insulin resistance and the metabolic alterations that occur during pregnancy." (PMID 40722699, 2025).
Insulin resistance (continued). "Considerably, hormonal imbalances, such as insulin resistance, altered adipokines, and inflammatory markers like highly sensitive-reactive protein (hs-CRP), IL-6, and TNF-α, are pivotal in fatty liver pathogenesis and cardiovascular risk." (PMID 39808219, 2025). "The activation of STAT3 stimulates the secretion of IL-6 and activates JNK, mTOR, and protein kinase C (PKC) signaling pathways, which aggravate insulin resistance." (PMID 40863244, 2025). "These microbial changes correlate with systemic inflammation, elevated IL-6, TNF-α, and CRP, as well as insulin resistance (HOMA-IR)." (PMID 40308637, 2025). "Visceral adipose tissue (VAT) is metabolically active, secreting pro-inflammatory cytokines such as interleukin-6 (IL-6) and tumor necrosis factor-alpha (TNF-α), thereby contributing to systemic inflammation and insulin resistance." (PMID 40521354, 2025). "Adipokines, including interleukin-6 (IL-6), tumor necrosis factor-alpha (TNF-α), and free fatty acids, can lead to insulin resistance, oxidative stress, and mitochondrial dysfunction that ultimately lead to renal damage." (PMID 40936744, 2025). "While IL-6 and TNF-α actively contribute to insulin resistance and ovarian dysfunction, CRP serves as an indicator of the overall inflammatory status." (PMID 40385768, 2025). "Excess adipose tissue, particularly visceral fat, induces insulin resistance through the release of pro-inflammatory cytokines such as tumor necrosis factor-alpha (TNF-α) and interleukin-6 (IL-6)." (PMID 41396032, 2025). "The most significant contributors to the development of insulin resistance are adiponectin, TNF-alpha, and IL-6, despite the fact that various other adipokines have been implicated in the pathogenesis of T2DM." (PMID 39791169, 2025). "In UC, the Th2/Th17 immune response extends beyond the gut, with cytokines like IL-6, TNF-α, and IL-17 playing a role in the development of adiposity and insulin resistance." (PMID 41007787, 2025). "Research confirms higher C-reactive protein (CRP) levels in MetS patients are correlated with insulin resistance, blood pressure, poor HDL, triglycerides, and proinflammatory cytokine levels, including TNF and IL-6." (PMID 39817379, 2025). "Persistent exposure to cortisol and pro-inflammatory cytokines such as IL-6 and TNF-α enhances adipocyte differentiation and hepatic lipid accumulation, amplifying insulin resistance and dyslipidemia." (PMID 41464283, 2025). "Nevertheless, adipose tissue, now recognized as an endocrine organ, secretes multiple adipokines (e.g., leptin, adiponectin, visfatin) and inflammatory mediators (TNF-α, IL-6, MCP-1) that foster insulin resistance and endothelial dysfunction." (PMID 40149704, 2025). "This reduction is thought to exacerbate insulin resistance by allowing the unchecked activity of pro-inflammatory cytokines such as TNF-α and IL-6, which impair insulin receptor signaling through pathways like NF-κB and JNK." (PMID 40804870, 2025). "Biomarkers such as CRP, IL-6, and TNF-α serve as indicators of inflammation, while HOMA-IR, fasting insulin, and HbA1c are essential for evaluating insulin resistance." (PMID 40002771, 2025). "Mechanistically, insulin resistance in T2DM promotes both adiposity and muscle catabolism, while chronic low-grade inflammation (e.g., elevated TNF-α and IL-6) accelerates muscle degradation." (PMID 40955268, 2025). "These important mechanisms are disruption of the blood-brain barrier, microglial activation, cytokine-related neurotoxicity (e.g., IL-6, TNF-alpha), lysosomal maladaptation, and metabolic imbalance (e.g., insulin resistance, hyperglycemia)." (PMID 40842786, 2025). "With regard to metabolic syndrome, elevated IL-18 levels can contribute to insulin resistance by increasing the production of other inflammatory cytokines like TNF-α and IL-6, which interfere with insulin signaling pathways." (PMID 40277935, 2025).
Insulin resistance (continued). "Primary outcomes included insulin resistance (HOMA-IR), insulin sensitivity (Matsuda index), mtDNA DAMPs (ND1, ND6), pro/anti-inflammatory cytokines (IFN-γ, IL-10, IL-6, IL-8, TNF-α), CRP, and cortisol." (PMID 41156500, 2025). "Further, a strong positive correlation between insulin resistance index (HOMA-IR) and IL-6, TNF-α, and MDA of liver." (PMID 40229885, 2025). "Adipose tissue—particularly visceral fat—secretes inflammatorycytokines (e.g., IL-6, TNF-α), activating the TLR4/NF-κBpathway, which induces insulin resistance, endothelial dysfunction, andatherosclerotic plaque formation." (PMID 41356294, 2025). "Another study uncovered that while adipose tissue IL-6 is the main contributor to insulin resistance, IL-1β and TNF-α cooperativity increase IL-6 expression by promoting CREB binding and H3K14 acetylation at the IL-6 promoter region." (PMID 41228440, 2025). "Pro-inflammatory cytokines IL-6, IL-1β, and TNF-α play a crucial role in MASLD-related inflammation and progression and hepatic insulin resistance." (PMID 40722894, 2025). "In our study, CDD effectively improved body weight, insulin resistance index, and ovarian function in PCOS-IR model mice, and significantly downregulated both mRNA and protein expression levels of the IL6/JAK2/STAT3/FOXO4 signaling pathway." (PMID 41573199, 2025). "Chronic inflammatory response exacerbates insulin resistance by triggering responses of C-reactive protein (CRP), tumor necrosis factor-alpha (TNF-α), and interleukin-6 (IL-6), resulting in T2DM and renal impairment and increasing uric acid levels." (PMID 40129592, 2025). "In diabetes, adipose tissue inflammation and high serum IL-6/TNF levels are well-documented, contributing to insulin resistance and also potentially affecting the brain and behaviour." (PMID 41149069, 2025). "Its anti-inflammatory properties also contribute to its metabolic benefits by suppressing pro-inflammatory cytokines (IL-6, TNF-α) and inhibiting the NF-κB and TLR4 signaling pathways, which are often upregulated in dyslipidemia and insulin resistance." (PMID 40509408, 2025). "An increased level of IL-17 activates an overabundant proinflammatory response by NF-kB signaling in adipose tissue, which results in the excessive production of IL-1β, IL-6, and TNF-α, contributing to insulin resistance." (PMID 40277935, 2025). "These include elevated renal acid load, increased uremic toxins, promotion of insulin resistance, and elevated levels of pro-inflammatory cytokines such as TNF-α and IL-6." (PMID 40871720, 2025). "Clinically, obese patients with T2DM exhibit elevated IL-6 and TNF-α, which correlates with the severity of insulin resistance." (PMID 41226411, 2025). "The increase in IL-6 and TNF-α in synchrony promotes the increase in C-reactive proteins and the decrease in adiponectin, which will increase the insulin resistance characteristic of a diabetic patient." (PMID 40141192, 2025). "Inflammatory mediators such as IL-6 and TNF-α contribute to skeletal muscle protein degradation, impair anabolic signaling, and exacerbate insulin resistance." (PMID 40708651, 2025). "Several myokines, including IL-6 and FGF-21, are known to be elevated in the context of insulin resistance." (PMID 40408301, 2025). "In contrast, IL-6 released from adipose tissue enhances free fatty acid (FFA) secretion through gp130, promoting diet-induced hepatic steatosis and insulin resistance in obese mice." (PMID 40864559, 2025). "Vitamin E has preventive and protective effects on MASLD by improving hepatic steatosis (FLI, L/S ratio), insulin resistance (HOMA-IR), oxidative stress (MDA), inflammation (hs-CRP, TNF-α, IL-6, leptin, adiponectin), and hepatocyte apoptosis (CK18-M30)." (PMID 40668532, 2025). "Specifically, IL-1β directly damages pancreatic β-cells, IL-6 affects glucose metabolism, and TNF-α plays a central role in peripheral insulin resistance." (PMID 39960958, 2025).
Insulin resistance (continued). "Insulin resistance is connected to increased TNF-α expression, and IL-6 plays a key role in lipid buildup in the myocardium." (PMID 39791169, 2025). "These inflammatory mediators, such as (but not limited to) TNFα, IL-6, and MCP-1, which are produced by myocytes or obese skeletal muscle, have been shown to contribute to impaired glucose uptake and insulin resistance." (PMID 38398822, 2024). "Second, the impact of inflammatory cytokines such as IL-6 and CRP is worth considering; these cytokines exacerbate atherosclerosis and insulin resistance, which are key mechanisms in CVD development." (PMID 38698329, 2024). "Several adipokines/cytokines such as leptin, resistin, retinol-binding protein 4 (RBP4), angiopoietin-like protein 2, IL-6 and MCP-1 promote the atherosclerotic process by inducing inflammation, endothelial dysfunction and insulin resistance." (PMID 39867890, 2024). "ROC: receiver operating characteristics, IL6: interleukin-6, HOMA-IR: homeostatic model assessment for insulin resistance." (PMID 39131026, 2024). "It was found that some key inflammatory mediators of COPD, particularly IL‐6, TNF‐α, and TGF‐β, also play hub roles in insulin resistance and diabetes." (PMID 39187923, 2024). "Our findings demonstrated that both 12 weeks of AT and saffron supplementation alone significantly affected serum levels of glucose, insulin resistance, FIB, HCY, IL‐6, and TNFα in diabetic patients." (PMID 38874882, 2024). "Given the close link between dyslipidemia, chronic low-grade inflammation, and insulin resistance, a comparative analysis of serum biochemical parameters (HDL-C, LDL-C, TC, TG) and plasma inflammatory factors (IL-6, TNF-α) was conducted." (PMID 38708085, 2024). "Significantly elevated levels of cytokines like IL-6 and TNF-α in the adipose tissue highlight an inflammatory milieu that further complicates insulin resistance, endothelial dysfunction, and other metabolic conditions." (PMID 39064298, 2024). "ROC: receiver operating characteristics, urine ACR: urine albumin creatinine ratio, IL6: interleukin-6, HOMA-IR: homeostatic model assessment for insulin resistance." (PMID 39131026, 2024). "Spinach aids insulin resistance by inhibiting increased levels of serum C-reactive protein, tumor necrosis factor (TNF)-α, and Interleukin-6." (PMID 39519546, 2024). "We also observed inverse correlations between several PCs and LPCs and fasting plasma glucose and insulin, as well as the homeostatic model assessment for insulin resistance (HOMA-IR) and inflammatory markers such as IL6 and C-reactive protein (CRP)." (PMID 39195560, 2024). "Firstly, as an active endocrine organ, VAT releases a plethora of inflammatory cytokines such as IL-6 and TNF-α, thereby inducing a low-grade inflammatory state and insulin resistance." (PMID 38685072, 2024). "One of the main pro-inflammatory cytokines, hepatic IL-6, is elevated in animal models of NAFLD, and chronic elevation in mice leads to systemic insulin resistance." (PMID 38535313, 2024). "This suggests that IL-6, IGF-1, and VEGF are important inflammatory factors promoting insulin resistance, and glucose fluctuations in diabetic cataracts and these factors are closely related to oxidative stress injury." (PMID 39015537, 2024). "Its anti-inflammatory effects are mediated through the downregulation of IL-6 and TNF-α and the upregulation of IL-10, thereby mitigating chronic inflammation that contributes to insulin resistance and β-cell dysfunction." (PMID 39796549, 2024). "Secondly, it induces insulin resistance by activating NF-κB and upregulating inflammatory factors such as TNF-α and IL-6." (PMID 40302954, 2024).